CYP11B1 (cytochrome P450 family 11 subfamily B member 1)
Description:
A cytochrome P450 monooxygenase mainly involved in the biosynthesis of adrenal corticoids. Catalyzes a variety of reactions that are essential for many species, including detoxification, defense, and the formation of endogenous chemicals like steroid hormones. Steroid 11beta, 18- and 19-hydroxylase with preferred regioselectivity at 11beta, then 18, and lastly 19 (By similarity). Catalyzes the hydroxylation of 11-deoxycortisol and 11-deoxycorticosterone (21-hydroxyprogesterone) at 11beta position, yielding cortisol or corticosterone, respectively, but cannot produce aldosterone. Mechanistically, uses molecular oxygen inserting one oxygen atom into a substrate for hydroxylation and reducing the second into a water molecule. Two electrons are provided by NADPH via a two-protein mitochondrial transfer system comprising flavoprotein FDXR (adrenodoxin/ferredoxin reductase) and nonheme iron-sulfur protein FDX1 or FDX2 (adrenodoxin/ferredoxin). Due to its lack of 18-oxidation activity, it is incapable of generating aldosterone. Besides its role in the biosynthesis of mineralocorticoids and glucocorticoids, it can also participate in the androgen metabolic pathway, converting androst-4-ene-3,17-dione to 11beta-hydroxyandrost-4-ene-3,17-dione, and testosterone (17beta-hydroxy-4-androsten-3-one) to 11beta,17beta-dihydroxyandrost-4-ene-3-one.
Synonyms: P450C11; FHI; CPN1; CYP11B
Tractability: Small molecule: an approved drug acts on it; a structure with a bound ligand is known; a high-quality ligand is known; it belongs to a druggable protein family. Antibody: UniProt places it where antibodies can reach, with medium confidence. PROTAC: a small molecule that binds it is known.
Target class: Cytochrome P450 family 11; Cytochrome P450 family 11B; Enzyme; Cytochrome P450; Cytochrome P450 11B1
Gene: Protein-coding gene on chromosome 8 (142,871,528 to 142,880,000, reverse strand). Ensembl gene ENSG00000160882.
Subcellular location: Mitochondrion inner membrane
Subcellular location (Human Protein Atlas): Mitochondria
Pathways (Reactome):
Metabolism: Endogenous sterols; Glucocorticoid biosynthesis
Disease: Defective CYP11B1 causes AH4
Gene Ontology:
Molecular function: steroid 11-beta-monooxygenase activity; corticosterone 18-monooxygenase activity; heme binding; iron ion binding; monooxygenase activity; oxidoreductase activity, acting on paired donors, with incorporation or reduction of molecular oxygen
Biological process: aldosterone biosynthetic process; C21-steroid hormone biosynthetic process; cellular response to hormone stimulus; cellular response to potassium ion; cortisol biosynthetic process; regulation of blood pressure; cellular response to peptide hormone stimulus; cholesterol metabolic process; cortisol metabolic process; glucocorticoid biosynthetic process; glucose homeostasis; immune response; sterol metabolic process
Cellular component: mitochondrion; mitochondrial inner membrane
Genetic constraint (gnomAD): Loss-of-function variants: 33 observed, 47.82 expected, observed/expected ratio (o/e) 0.69, 90% interval 0.52 to 0.92. The upper end of that interval is the gene's LOEUF score, 0.92, which puts it in group 3 of 6, group 1 being the genes least tolerant of losing a copy. Missense variants: 688 observed, 669.53 expected, observed/expected ratio (o/e) 1.03, 90% interval 0.96 to 1.09. Synonymous variants: 289 observed, 269.42 expected, observed/expected ratio (o/e) 1.07, 90% interval 0.97 to 1.18.
Homologues: Orthologues: chimpanzee CYP11B1 (99% identical), macaque CYP11B1 (97% identical), macaque CYP11B2 (93% identical). Paralogues in human: CYP11B2 (93% identical), CYP11A1 (38% identical).
Diseases named in the same sentence as CYP11B1 in open-access papers:
CYP11B1 is named in the same sentence as 79 diseases in open-access papers, as found by Europe PMC text mining. Sharing a sentence is not in itself a finding about the gene and the disease. The quoted sentences say what the papers report.
adenoma (27 papers, 2013 to 2025). A neoplasm arising from the epithelium. "Three IHC patterns were identified: CYP11B2-positiveadenomas, mixed CYP11B1/CYP11B2 adenomas, and multiple small CYP11B2-positivenodules." (PMID 41196931, 2025). "Conversely, CYP11B1 score was higher in those with a CYP11B2-negative adenoma than in the remaining patients (120.0 (10.0–90.0) vs 30.0 (70.0–180.0), P < 0.001)." (PMID 38051154, 2024). "Our study included a review of 20 previously documented cases of aldosterone- and cortisol-producing adenomas (A/CPAs), two of which were concurrently positive for both CYP11B1 and CYP11B2, consistent with our findings." (PMID 39010034, 2024). "Our results showed statistical difference between two groups but the AUC value was relatively low, suggesting that CYP11B1 had potential for distinguishing carcinomas from adenomas." (PMID 38802933, 2024). "A close association between a low DNA methylation ratio and an increased CYP11B1 expression is seen in Cushing’s adenoma and aldosterone-producing adenoma with autonomous cortisol secretion." (PMID 36982850, 2023). "These adenomas exhibited cytoplasmic and/or nuclear beta-catenin expression as well as a variable expression of CYP11B1 (typically expressed in ZF layer) and CYP11B2 (typically expressed in ZG layer) by immunohistochemistry." (PMID 29594118, 2018). "Patient 10 had two adenomas with different staining patterns, the adenoma with stronger staining for CYP11B1 was defined as the culprit lesion and used in the following experiments." (PMID 28894201, 2017). "Further support to the activation of SF-1 in the rat tumors came from the validation of Cyp11b1 and Cyp11b2 overexpression in independent adenoma samples." (PMID 23756599, 2013). "We reported that higher mRNA levels of CYP11B1 were associated with a lower methylation ratio in CPAs compared to adrenal tissues or non-functioning adenomas." (PMID 39596027, 2024). "This might partially be explained by the higher CYP11B1 scores in adrenal samples with CYP11B2-negative adenomas, implicating possible cortisol cosecretion." (PMID 38051154, 2024). "The histopathological characterization of aldosterone and cortisol co‐secreting adenoma could show ZF and ZG like cells, respectively, while CYP11B1 and CYP11B2 immunostaining demonstrated heterogeneity." (PMID 34657370, 2021). "Protein kinase A catalytic alpha subunit is a disease driver in 30–40% of cortisol-producing adenoma (CPA) and was associated with reduced DNA methylation at the CYP11B1 promoter that may result in CYP11B1 transcription and hypercortisolemia." (PMID 29794126, 2018). "However, other studies showed that the immunoreactivity of CYP11B1 was relatively low in adenomas without KCNJ5 mutations." (PMID 36950676, 2023). "The aims of our study were to determine whether the CYP11B1 expression was regulated through DNA methylation in hypercortisolemia with cortisol-producing adenoma (CPA), and to investigate a possible relationship between DNA methylation and somatic mutations identified in CPA." (PMID 28894201, 2017). "Immunohistochemical staining revealed that the left adenoma primarily comprised clear cells expressing CYP11B2, whereas the right adenoma comprised both eosinophilic compact and clear cells expressing CYP11B1." (PMID 36960396, 2023). "The mRNA levels of steroidogenic enzymes (including CYP11B1 and CYP17A1) were high in the right adenoma, whereas CYP11B2 was highly expressed in the left adenoma." (PMID 36960396, 2023). "We also analyzed the expression of cortisol-producing CYP11B1 and aldosterone-producing CYP11B2 enzymes in adenoma tissue from 57 patients with aldosterone-producing adenoma, employing immunohistochemistry with digital image analysis." (PMID 28422753, 2017). "We reported higher mRNA levels of CYP11B1 in concomitant with a lower methylation ratio in CPAs compared to adrenal tissues or nonfunctioning adenomas." (PMID 36982850, 2023).
adenoma (continued). "In MATCH, we compared the in vivo uptake of [11C]metomidate into APAs, non-aldosterone-producing adenomas and the adjacent adrenal, correlating with measurements of CYP11B1 and CYP11B2 expression of each region by quantitative PCR or RNA-seq." (PMID 36646800, 2023). "Our result showed no immunoreactivity of CYP11B1 and weak immunoreactivity of CYP17A1 presented in this KCNJ5 157-159delITE mutated adenoma." (PMID 34440230, 2021). "For other steroidogenesis related enzymes, such as 3β-Hydroxysteroid dehydrogenase (HSD3B), 17α-hydroxylase (CYP17A1), and 11β-hydroxylase (CYP11B1), their IHC staining was not enhanced in the adenoma, but was observed in the adjacent adrenal gland tissues." (PMID 34572956, 2021). "CYP11B1 was the steroidogenic enzyme with the most discriminative power to distinguish ACC from ACAc, with a sensitivity of 100%, specificity of 92%, and an expression higher than 4.44%, indicating the presence of a cortisol secreting adenoma." (PMID 32751564, 2020). "In our case, immunohistochemical analysis and mRNA levels of steroidogenic enzymes revealed a left adenoma that primarily consisted of clear cells and mainly expressed CYP11B2, whereas the right adenoma was composed of both eosinophilic compact and clear cells and mainly expressed CYP11B1." (PMID 36960396, 2023). "However, immunohistochemistry reveals that APA consists of CYP11B2-positive cells, CYP11B1-positive cells, and double negative cells, whereas non-functional adenomas only comprise CYP11B1-positive cells and double negative cells and did not harbor CYP11B2-positive cells." (PMID 33437027, 2021). "CYP11B1 and CYP17A1 were highly expressed in the right adenoma and CPAs, whereas CYP11B2 was highly expressed in the left adenoma and APAs compared with other adrenal diseases and nonfunctional adenoma." (PMID 36960396, 2023). "In contrast, tumors that are composed predominantly of ZG-like compact cells are typically enriched in ATP1A1-, ATP2B3-, and CACNA1D-mutant aldosterone-producing adenomas that show increased and strong CYP11B2 expression and predominantly negative CYP11B1 or CYP17A1 expression profiles." (PMID 29594118, 2018).
congenital adrenal hyperplasia (27 papers, 2015 to 2025). Congenital adrenal hyperplasia (CAH) is an inherited endocrine disorder caused by a steroidogenic enzyme deficiency that is characterized by adrenal insufficiency and variable degrees of hyper or hypo androgyny manifestations, depending of the type and the severity of the disease. "11β-Hydroxylase deficiency (11β-OHD) caused by mutations in the CYP11B1 gene is the second most common form of congenital adrenal hyperplasia." (PMID 35685215, 2022). "Congenital adrenal hyperplasia (CAH) resulting from steroid 11β-hydroxylase deficiency (11β-OHD) is caused by mutations in the CYP11B1 gene." (PMID 30241518, 2018). "11β-Hydroxylase deficiency (11OHD) is a common form of congenital adrenal hyperplasia that has been shown to result from inactivating CYP11B1 mutations, and pathogenic CYP11B2/CYP11B1 chimeras contribute to a minority of cases." (PMID 29703198, 2018). "Mutations in 11β-hydroxylase (CYP11B1, the last enzyme in the glucocorticoid pathway) cause congenital adrenal hyperplasia." (PMID 29046340, 2018). "A missense G > A SNP (Arg > Gln) in exon 7 of the CYP11B1 gene, involved in the biosynthesis of adrenal corticoids, has been found to contribute to congenital adrenal hyperplasia and associated gynecomastia, empty scrotum, and aggressive behavior in a tomcat with a normal 38,XY chromosome set14." (PMID 36280698, 2022). "11-beta hydroxylase deficiency (11βOHD) is a rare variant of congenital adrenal hyperplasia (CAH), resulting from mutations in the CYP11B1 gene." (PMID 41234966, 2025). "Congenital Adrenal Hyperplasia (CAH) due to CYP11B1 is a rare autosomal recessive adrenal disorder that causes a decrease in cortisol production and accumulation of adrenal androgens and steroid precursors with mineralocorticoid activity." (PMID 36589846, 2022). "For example, deficiency in the enzymes regulating cortisol biosynthesis, such as Cytochrome P450 Family-11-Subfamily-B-Member-1 (CYP11B1) lead to congenital adrenal hyperplasia." (PMID 38764035, 2024). "Congenital adrenal hyperplasia (CAH) is a group of autosomal recessive disorders caused by pathogenic variants identified in seven genes (CYP21A2, CYP11B1, CYP17A1, HSD3B2, StAR, POR, and CYP11A1) involved in the steroidogenesis pathway." (PMID 39451515, 2024). "The overall percent of cells staining positive for CYP11B1 was low on any given section-likely because the patients had adrenal hyperplasia and increased ZR, accounting for the overall low CYP11B1 presence." (PMID 34616364, 2021). "HSD3B2, CYP17A1, CYP21A2, CYP11B1 and POR mutations give rise to four variants of congenital adrenal hyperplasia (OMIM 201810, 202110, 201910, 202010, and 201750 respectively) and CYP11B2 mutations give rise to hypoaldosteronism (OMIM 203400)." (PMID 29046340, 2018). "Congenital adrenal hyperplasia (CAH) due to steroid 11β-hydroxylase deficiency is the second most common form of CAH, resulting from a mutation in the CYP11B1 gene." (PMID 26265915, 2015). "11β-hydroxylase deficiency (11β-OHD) caused by mutations in the CYP11B1 gene accounts for approximately 5–8 % of congenital adrenal hyperplasia (CAH) in non-consanguineous populations, but accounts for ~15 % of cases in both Muslim and Jewish Middle Eastern populations." (PMID 27316665, 2016). "Congenital adrenal hyperplasia (CAH) refers to a group of seven monogenic adrenal disorders, caused by pathological variants in genes coding for enzymes in the adrenal steroidogenic pathway: CYP21A2, CYP11B1, CYP17A1, HSD3B2, STAR, CYP11A1, and POR." (PMID 41450580, 2025). "Congenital adrenal hyperplasia (CYP21A2, CYP11B1, HSD3B2, CYP17A1, POR defects) constitutes the largest subgroup of impaired steroidogenesis and represents the most common cause of PAI in children." (PMID 27485500, 2016).
congenital adrenal hyperplasia (continued). "Furthermore, these findings match with our earlier observations showing an evident adrenal hyperplasia accompanied by an enhanced steroidogenic machinery since StAR, CYP11A1, CYP11B1, and 11β-HSD1 expression are increased in this period." (PMID 31998227, 2019).
Hypertension (27 papers, 2009 to 2026). The presence of chronic increased pressure in the systemic arterial system. "Subsequently, it was found that salt-sensitive rats have the allele of the gene encoding 11B-hydroxylase (CYP11B1), an enzyme necessary for the synthesis of a steroid that stimulates salt retention, which is responsible for the development of hypertension." (PMID 40722594, 2025). "Posaconazole and itraconazole were recently found to cause pseudohyperaldosteronism with hypokalemia and hypertension by inhibiting CYP11B1-dependent adrenal cortisol biosynthesis." (PMID 37637492, 2023). "A multitargeted interaction-based degree algorithm and a phylogenetic tree of pathways showed that the NR3C1, REN, PPARG, and CYP11B1 hub genes were consistently modulated by Υ-sitosterol to reduce hypertension and related risk factors." (PMID 37571339, 2023). "We also analyzed the correlation between CYP11B1 polymorphisms and IS risk stratified by smoking and hypertension." (PMID 36532271, 2022). "We further analyzed the impact of CYP11B1 SNPs on risk factors (gender, age, alcohol intake, smoking, and hypertension) for patients with IS." (PMID 36532271, 2022). "The relationship between CYP11B1 polymorphisms and the risk of ischemic stroke complicated with hypertension." (PMID 36532271, 2022). "Glucocorticoid-remediable aldosteronism (GRA) is a form of heritable hypertension caused by a chimeric fusion resulting from unequal crossing over between 11β‐hydroxylase (CYP11B1) and aldosterone synthase (CYP11B2), which are two genes with similar sequences." (PMID 35012455, 2022). "Glucocorticoid-Remediable Aldosteronism, a rare form of hypertension, is caused by a gene fusion between CYP11B1 and CYP11B2." (PMID 24658007, 2014). "Mutations in the gene coding for 11β-hydroxylase, Cyp11b1, were the first to be linked to the development of hypertension in the Dahl S rat." (PMID 23130148, 2012). "CALCRL (calcitonin receptor-like) is a multifunctional vasodilator peptide that was persistently upregulated in aged rats whereas Cyp11b1 is associated with essential hypertension and had decreased levels in both age groups." (PMID 23251410, 2012). "Another set of genes (CYPD6 and CYPD7) are involved in a gene conversion that causes debrisoquine polymorphism and a gene conversion between CYP11B2 and CYP11B1 has been linked to causing hypertension." (PMID 20148076, 2009). "In this study, participants 10 and 12 were reported to have uncontrolled hypertension, which can be reported in disorders of steroidogenesis, such as 11-beta-hydroxylase deficiency, caused by biallelic variants in the CYP11B1 gene, a downstream target of FDXR in the adrenal gland." (PMID 39669623, 2024). "Several genes, including CYP17A1, CYP11B2, HSD11B1, CYP11B1, and NR3C2, which are implicated in the control of hypertension, regulate the synthesis of steroid hormones, such as glucocorticoids, mineralocorticoids, androgens, and estrogens." (PMID 37571339, 2023). "The emergence and progression of hypertension have been linked to the genes HIF1A, CYP11B1, and NR3C1." (PMID 37571339, 2023). "NR3C1, REN, PPARG, and CYP11B1 were identified as critical targets (36-degree value) in the network for hypertension progression because of this conformity." (PMID 37571339, 2023). "Further investigation of the interplay between CYP11B1, testosterone, and high blood pressure in the context of biological sex is warranted." (PMID 36635277, 2023). "In females, six loci (P < 5 × 10−8) were shared between testosterone and high blood pressure, and 3 (CYP11B1, SLC16A1, SLC22A7) of them were in DMET gene regions." (PMID 36635277, 2023). "In CYP11B1 deficiency, a decrease in ACTH also results in a decrease of mineralocorticoid precursors preventing the development of hypertension." (PMID 36589846, 2022). "The correlation between CYP11B1 polymorphisms and CHD risk was further analyzed in different subgroups (age, gender, hypertension and diabetes)." (PMID 35831903, 2022).